VIM (vimentin)
Diseases named in the same sentence as VIM in open-access papers (continued):
Sharing a sentence is not in itself a finding about the gene and the disease.
endometrial adenocarcinoma (9 papers, 2007 to 2025). "For example, an endocervical GAS is distinguished from an endometrial adenocarcinoma by ER/PR/vimentin negativity, expression of gastric mucins (MUC6/HIK1083), and absence of CD10." (PMID 40732715, 2025). "In this study, it was confirmed that the expression of miR-543 was upregulated, while the expression of α-SMA, vimentin, and fibronectin was decreased in endometrial epithelial cells and endometrial adenocarcinoma cells." (PMID 33860034, 2021). "When the expression of miR-543 was inhibited, the expression of α-SMA, vimentin, and fibronectin in primary endometrial epithelial cells and endometrial adenocarcinoma cells increased." (PMID 33860034, 2021). "Vimentin expression was expected since it has also been consistently demonstrated in endometrial adenocarcinomas." (PMID 17645802, 2007). "In endometrial epithelial cells and endometrial adenocarcinoma cells, after the overexpression of miR-543, the mRNA expression of vimentin, COL16A1, α-SMA, and Fibronectin decreased, while the mRNA expression of CDH1 increased, while miR-543 inhibitor played the opposite role." (PMID 33860034, 2021). "A recent study has shown that SAHA could induce EMT in human endometrial adenocarcinoma cell line (Ishikawa cells), which was consistent with up-regulation of N-cadherin and vimentin with concomitant down-regulation of E-cadherin and increased cell motility." (PMID 23024790, 2012). "While endocervical adenocarcinomas express p16 and CEA and whereas endometrial adenocarcinomas usually showed vimentin and hormonal receptors, the results may be inconclusive." (PMID 20199664, 2010). "However, CEA has been reported to be expressed in both cervical and endometrial adenocarcinomas, while the expression of vimentin was noted to be weak and focal in many endometrial adenocarcinomas." (PMID 20199664, 2010). "- Hormone receptors and vimentin: ER and PR are generally absent in HPV-negative GAS or MNAC, while vimentin expression is typical of endometrial adenocarcinomas." (PMID 40732715, 2025). "Poorly differentiated endometrial adenocarcinoma was histologically similar to H-FLAC, but in immunohistochemistry, endometrial adenocarcinoma was positive for ER, PR, and vimentin, but negative for TTF-1 expression." (PMID 35356917, 2022).
endothelial dysfunction (9 papers, 2016 to 2025). In vascular diseases, endothelial dysfunction is a systemic pathological state of the endothelium (the inner lining of blood vessels) and can be broadly defined as an imbalance between vasodilating and vasoconstricting substances produced by (or acting on) the endothelium. "In addition to endothelial dysfunction, repeated vascular injury provokes endothelial cells to acquire mesenchymal phenotype, expressing various markers (e.g. alpha‐smooth muscle actin, vimentin and fibronectin) that would drive aberrant activation of the epithelial‐mesenchymal trophic unit." (PMID 36908040, 2023). "Increased vimentin and α-SMA expression were detected in the vasculature, indicating endothelial dysfunction and myofibroblast activation, alongside a decrease in CD31 expression, consistent with an endothelial-to-mesenchymal transition (EndMT)." (PMID 41227327, 2025). "Many cytokines such as TNF-alpha, IL-1, IL-2, IL-4, IL-6, IL-18, monocyte chemoattractant protein-1 (MCP-1), vimentin, and platelet-derived growth factor (PDGF) are produced by macrophages and T lymphocytes activated due to endothelial dysfunction and oxidative stress." (PMID 34349888, 2021). "Knockout of vimentin, but not of synemin, resulted in increased carotid stiffness and contractility and endothelial dysfunction, independently of blood pressure and the collagen/elastin ratio." (PMID 28912461, 2017). "Impaired collagen expression and modification as well as lack of vimentin result in destabilisation of endothelial cells and integrity, provoking endothelial dysfunction which we were able to detect." (PMID 27898103, 2016).
Gliosis (9 papers, 2017 to 2024). Gliosis is the focal proliferation of glial cells in the central nervous system. "Of note, other gliosis-related gene, Vimentin, was also down-regulated by 0.78 and 0.70 times in HM-SI-14d and HM-SI-28d groups respectively." (PMID 38414051, 2024). "The changes in the expression of GFAP and vimentin in the tegmentum of chum salmon juveniles are similar to gliosis in mammals; however, scar formation in chum salmon juveniles is weak, which is consistent with data on other fish species." (PMID 31991815, 2020). "Gliosis is accompanied by the higher generation of the intermediate filament including GFAP, nestin, and vimentin, which leads to greater and more highly condensed glial processes and fibers." (PMID 38630361, 2024). "Müller cells undergo a process of activation, also known as gliosis, which is characterized mainly by an overexpression of intermediate filament proteins, such as GFAP and vimentin." (PMID 36671565, 2023). "However, in contrast to the observed downregulation of ITGB1, GFAP and vimentin, two prototype markers of gliosis, were not changed by modifying glucose levels in RMG." (PMID 34046254, 2021). "Gliosis is accompanied by the emergence of reactive astrocytes and can be determined not only by an increased number of GFAP positive (GFAP+) cells but also by the upregulation of other IFs like vimentin and nestin, as well as a rise of proliferating Ki67 positive cells." (PMID 28841900, 2017).
Granuloma (9 papers, 2017 to 2025). A compact, organized collection of mature mononuclear phagocytes, which may be but is not necessarily accompanied by accessory features such as necrosis. "In a recent publications, it was shown in a mice model that in vimentin-immunization mice granulomas were found in the lung following intervenous challenge with vimentin-coated beads." (PMID 37109576, 2023). "Recently, computational experimentation and wet-lab experimental approaches demonstrated the possibility of transforming vimentin-rich macrophages, which can differentiate into the myofibroblasts like cells around the macrophage aggregates in the later stages of granuloma formation." (PMID 35573702, 2022). "Furthermore, calf granulomas showed lower immunolabeling of MAC387+, CD79+, and WC1+ cells without connective tissue surrounding the lesion and were associated with less vimentin, Alpha Smooth Muscle Actin (α-SMA), and TGF-β compared with granulomas from adult cattle." (PMID 37180066, 2023). "In addition to host-pathogen interactions, vimentin may also affect the subsequent pathological features of infection in the lung, such as granuloma formation." (PMID 35573702, 2022). "Some cells that we identified as being in the fibrotic cuff of the granuloma slice were only positive for vimentin, CD11c, or αSMA, however we observed that most of the spindeloid-shaped fibroblasts-like cells in the fibrotic cuff that were positive for CD11c, αSMA, and vimentin." (PMID 33370784, 2020). "Surprisingly, vimentin and α-SMA immunolabeling of early-stage granulomas from calves was similar to that of adult cattle." (PMID 37180066, 2023). "Then, they analyzed the effects of exposition to vimentin in pre-immunized mice to vimentin itself and in non-immunized controls mice: lung histopathology examination showed that granulomas in vimentin-immunized mice were significantly larger than those in controls (p < 0.0001)." (PMID 36148452, 2022). "Positive vimentin fibroblasts formed cell layers with different thicknesses comprising the capsule of connective tissue around granulomas in stages III and IV of adult cattle; this distribution of fibroblasts around the lesions was absent in calf granulomas." (PMID 37180066, 2023).
heart failure (9 papers, 2013 to 2025). Inability of the heart to pump blood at an adequate rate to meet tissue metabolic requirements. "Immunofluorescence showed that ADAMTS8 and vimentin were significantly increased in patients with heart failure." (PMID 35224040, 2022). "In normal cardiac tissue, vimentin-positive cells are spread among cardiomyocytes, forming a delicate stroma, the amount of which increases with progressing heart failure." (PMID 27980728, 2016). "During heart failure, the pattern of desmin, vimentin, periostin and caspase-3 expression alters in the left atrium, regardless of the cause." (PMID 27980728, 2016). "The levels of this protein are reported to increase along with other cytoskeletal proteins such as tubulin, vinculin and vimentin under conditions of idiopathic dilated cardiomyopathy and also during transition from compensated ventricular hypertrophy to heart failure." (PMID 23706090, 2013). "Consistently with the mouse heart data, immunofluorescence staining data showed that the expression of VIM, PDGFRA and POSTN were significantly increased in the heart failure group compared with the normal heart." (PMID 36805782, 2023). "Similarly, vimentin is reported to increase in patients with dilated cardiomyopathy which may reflect activation of interstitial cells and fibrosis during the transition to heart failure." (PMID 25249829, 2014).
kidney tumor (9 papers, 2007 to 2023). "We show that tuberin deficiency is associated with increased expression of fibrosis protein (vimentin) and decreased expression of cell adhesion protein (N-cadherin) in kidney tumor tissue of patients with TSC." (PMID 25149531, 2014). "We found morphological and immunohistochemical features (PAX8, cytokeratin 8–18, cathepsin-K clone 3F9 positivity, and vimentin negativity) overlapping with those observed in the primary renal tumors." (PMID 37938323, 2023). "Together, these data show that tuberin is a key molecule in regulating cell fibrosis such as N-cadherin and vimentin in kidney tumor of TSC patients." (PMID 25149531, 2014). "The cytoplasm of kidney tumor cells stained positively for cytokeratin and vimentin, which are intermediate filaments proteins belonging to the cell cytoskeleton, and known to be co-expressed by various forms of RCC." (PMID 17212824, 2007). "In addition, the immunofluorescence staining data confirmed the decreased expression of N-cadherin and increased expression of vimentin in kidney tumor tissues of TSC patients." (PMID 25149531, 2014). "The renal tumors, including the skull and liver metastases, showed immunoexpression PAX8, CK8-18, and cathepsin-K, and negativity for vimentin." (PMID 37938323, 2023). "Human kidney tumor is stained for CD31 (mouse antibody) in green, Vimentin (guinea pig antibody) in red, E-Cadherin (mouse antibody) in white, and PCNA (mouse antibody) in magenta plus DAPI in blue." (PMID 25826597, 2015). "Kidney tumors from TSC patients showed significant decrease in N-cadherin and significant increased in vimentin protein expression compared to control kidney tissues." (PMID 25149531, 2014). "This analysis showed that the vimentin and β2-microglobulin genes were upregulated in renal tumors of F2 mice (n = 12) compared to normal renal tissue (not shown)." (PMID 24148528, 2013).
Myocardial fibrosis (9 papers, 2016 to 2025). "Fibrotic and extracellular remodeling markers Tgfβ1, Mmp2, Timp1, Col1a1, Col3a1, fibronectin and vimentin demonstrated a complex balance underlying myocardial fibrosis at different overload stages." (PMID 31181097, 2019). "By using some natural drugs such as Dendrobium officinale (DOE) on myocardial fibrosis in mice, DOE can suppress fibrosis by inhibiting EMT and EMT-related signaling molecules (such as TGF-β1, p-JNK, Twist, Snail1, Vimentin, etc.)." (PMID 40423444, 2025). "Inhibition of miR-195-5p reduced cardiac dysfunction, myocardial fibrosis, collagen deposition, and EndMT, promoted CD31 and VE-cadehrin expressions, and inhibited α-SMA and vimentin expressions." (PMID 34658906, 2021).
pancreatic adenocarcinoma (9 papers, 2010 to 2025). "In an independent study of 174 pancreas adenocarcinoma patients, a mesenchymal tumor phenotype (defined as loss of E-cadherin and gain of vimentin expression) was associated with poor prognosis." (PMID 29472531, 2018). "The presence of vimentin-expressing tumour epithelial cells in surgically resected pancreatic adenocarcinomas independently predicted a shorter postsurgical survival." (PMID 21448168, 2011). "In all, 45% of primary pancreatic adenocarcinomas contained neoplastic cells that expressed vimentin, and in 27.5% of the cancers >10% of cells expressed vimentin." (PMID 21448168, 2011). "Also, CD44 expression correlates with high Ki67, vimentin positivity, and N stage and may represent a potential target of novel therapeutic modalities in pancreatic adenocarcinoma patients." (PMID 28421110, 2017). "The expression levels of Twist1, TGF‐β, E‐cadherin, N‐cadherin, miR‐21, snail, slug, vimentin and VISTA genes were examined in pancreatic adenocarcinoma (PAAD) and normal pancreatic tissues by using the GEPIA2 database." (PMID 40344465, 2025). "In their study including 14 patients with pancreatic adenocarcinoma, Watanabe et al7 observed that HMGA2 and vimentin expression increased while E-cadherin expression decreased using Western blot analysis when the RAS/MEK pathway was inhibited." (PMID 37787719, 2023). "Finally, vimentin staining is normally positive in RCC, occurring in >90% of cases, while it is non-reactive in more than 90% of pancreatic adenocarcinomas." (PMID 20302679, 2010).
serous ovarian carcinoma (9 papers, 2015 to 2025). "In high-grade serous ovarian cancer, the overexpression of the CD73 molecule with EMT markers (e.g., Snail, vimentin, or Twist1) was associated with poor prognosis of survival." (PMID 38791431, 2024). "Another study assessed the protein expression of E-CADH, N-CADH, P-cadherin, ZEB1, HMGA2, RAB25, CD24, NCAM, SOX11, and VIM in 100 tubo-ovarian serous carcinoma effusions and found a limited prognostic role of the markers alone or in combination." (PMID 34070214, 2021). "Moreover, CSCs expressing vimentin, NANOG and other markers of pluripotency were found in tumor tissue sections of women with high grade serous ovarian carcinoma." (PMID 32679765, 2020).
ZIKV infection (9 papers, 2020 to 2026). "For instance, during dengue and Zika virus infections, intermediate filaments protein vimentin and nestin dynamically rearrange to form cage-like structures that contain perinuclear viral factories, facilitating viral replication." (PMID 40070659, 2025). "In contrast, during ZIKV infection, vimentin interacts with endoplasmic reticulum (ER)-resident RNA-binding proteins, such as RRBP1, suggesting a role in regulating the host RNA-binding environment to support viral replication." (PMID 41516263, 2025). "Upon ZIKV infection, the cytoskeleton proteins in the control cells were redistributed: a large proportion of F-actin, tubulin, and vimentin were relocalized to the perinuclear region; particularly, a cage-like structure clustering of tubulin was formed around nucleus." (PMID 38177122, 2024). "Vimentin intensity was also 2.59-fold increased after ZIKV infection." (PMID 31988337, 2020). "GFAP and vimentin increase found in infected astrocytes suggest that ZIKV infection could be actively inducing a reactive state." (PMID 31988337, 2020). "The discovery that vimentin filaments help to form complete and dense intracellular viral replication factories for viral production in both physical space and biological regulation suggests that vimentin could be a potential host target for ZIKV infection treatment." (PMID 40070659, 2025). "Within host cells, the cytoskeletal vimentin intermediate filament network facilitates viral replication during DENV and ZIKV infection by shrinking and forming a cage-like structure." (PMID 41137718, 2026). "Vimentin expression in uninfected cells increased after 3 days of culture, whereas ZIKV infection did not alter its expression; heparin addition after infection accelerated hf-NPC differentiation." (PMID 36121298, 2022). "Notably, vimentin cage assembly during ZIKV infection does not involve phosphorylation at Ser39, Ser56, or Ser83, indicating a phosphorylation-independent mechanism of vimentin remodeling." (PMID 41516263, 2025).
chronic obstructive pulmonary disease (8 papers, 2014 to 2025). A chronic and progressive lung disorder characterized by the loss of elasticity of the bronchial tree and the air sacs, destruction of the air sacs wall, thickening of the bronchial wall, and mucous accumulation in the bronchial tree. "Citrulline 71 in vimentin was also recently detected in lung tissue samples, including those from smokers and patients with chronic obstructive pulmonary disease." (PMID 29084415, 2017). "For instance, decreased expression of E‐cadherin, together with an increase in Vimentin—a mesenchymal marker—was found in the lung tissues of patients with chronic obstructive pulmonary disease (COPD) exhibiting an inverse relationship between blood cadmium concentration and respiratory function." (PMID 40623872, 2025). "In chronic obstructive pulmonary disease (COPD) patients and smokers, vimentin levels are increased." (PMID 34638916, 2021). "In this study we set out to evaluate the biological relevance and serum biomarker potential of citrullinated vimentin (VICM) and non-citrullinated vimentin (VIM) in non-small cell lung cancer (NSCLC) and chronic obstructive pulmonary disease (COPD)." (PMID 31827725, 2019).
Cirrhosis (8 papers, 2019 to 2026). A chronic disorder of the liver in which liver tissue becomes scarred and is partially replaced by regenerative nodules and fibrotic tissue resulting in loss of liver function. "To further refine the stratification of HCC subtypes, we also used vimentin (VIM) and TGF-β, typically associated with stromal fibrosis of the HCC tissues and cirrhosis, as well as scirrhous HCC subtype." (PMID 41522204, 2026). "In patients with cirrhosis, 2 (7%) out of 28 presented evidence of CTCs, and 1 of them also presented high vimentin levels." (PMID 36286037, 2022). "For confirming the in vitro results on HBV-induced vi-VIM upregulation, HBV-uninfected and -infected human liver tissues with progressing disease (i.e., CHB, and cirrhosis) were stained with the mVSF antibody during IHC or immunofluorescence." (PMID 34571970, 2021). "Our further investigation into the association between these DEGs and immune infiltration also revealed the correlations between ACTB, TAGLN, VIM, SOX9 and immune cells, supporting that these genes play a vital role in cirrhosis via regulating immune infiltration." (PMID 36725885, 2023). "In addition, we examined the expression distribution of SNAI1, ZEB2, and VIM, which are the top three markers exhibiting strong correlation with KLF2, in the GSE25097 dataset related to cirrhosis development." (PMID 37386390, 2023).